PIGA (phosphatidylinositol glycan anchor biosynthesis class A)
Diseases named in the same sentence as PIGA in open-access papers (continued):
Sharing a sentence is not in itself a finding about the gene and the disease.
adenoma (1 paper, 2024). A neoplasm arising from the epithelium. "Although the PIGA mutant allele frequency varied considerably between adenomas, it was above the median mutant allele frequency for the corresponding adenoma in most cases, a pattern similar to APC, and consistent with occurrence early in tumorigenesis." (PMID 38546397, 2024). "To further assess aberrant cellular processes in adenomas with PIGA mutations, we identified 88 genes that were overexpressed and 1,325 genes that were downregulated." (PMID 38546397, 2024). "Flow cytometry analysis of two FAP adenoma-derived duodenal organoid lines indicated that their PIGA mutations resulted in complete loss of GPI anchors on the cell membrane." (PMID 38546397, 2024). "The VAFs associated with PIGA variants in this study suggest that the variants may arise early in duodenal adenoma development in a proportion of already initiated adenomas, perhaps following APC initiating events but preceding those affecting other known tumor drivers such as KRAS." (PMID 38546397, 2024). "For 21 adenomas with both WES and WTS data, the latter was used to confirm the APC, PIGA, and KRAS mutations identified by WES, with concordant findings in all cases." (PMID 38546397, 2024). "The digestive brush-border enzyme ALPI is a marker of enterocytes and a GPI-AP downregulated in PIGA-mutant adenomas, indicating potential for enterocyte dedifferentiation to an immature crypt phenotype." (PMID 38546397, 2024). "Two of the mutant lines contained naturally occurring somatic PIGA point mutations and two (lines 10 and 11) were generated by CRISPR from one of the PIGA wild-type adenoma-derived organoids (line 7)." (PMID 38546397, 2024). "Although most (12/19) adenomas with PIGA mutations were tubular adenomas (TA) with low-grade dysplasia (LGD), 3/5 adenomas with high-grade dysplasia in the study had PIGA mutations (P = 0.119) as did 4/9 with tubulovillous or villous histology." (PMID 38546397, 2024). "Sixteen of these DEGs (all downregulated in PIGA mutant adenomas) were known GPI-APs." (PMID 38546397, 2024). "Flow cytometry of PIGA-mutant adenoma-derived and CRISPR-edited duodenal organoids confirmed loss of GPI anchors in duodenal epithelial cells and transcriptional profiling of duodenal adenomas revealed transcriptional signatures associated with loss of PIGA." (PMID 38546397, 2024). "In MAP adenomas, the Muts/Mb was also not significantly different between PIGA mutated and nonmutated adenomas (4.7Muts/Mb vs. 4.2Muts/Mb, P = 0.83)." (PMID 38546397, 2024).
atrial septal defect (1 paper, 2024). Interauricular communication is a congenital malformation characterized by a communication between the atrial chambers of the heart. "In some patients, pathogenic variants in PIGA were associated with cardiac anomalies, especially atrial septal defects." (PMID 39766333, 2024).
Burkitt lymphoma (1 paper, 2021). A rare form of malignant mature B-cell non-Hodgkin lymphoma. "A previous study demonstrated that a substrain of Burkitt lymphoma Ramos cells [Ramos(-)] lacked GPI-anchored protein expression on the cell surface, which could be restored by transfecting the cells with PIGA cDNA18." (PMID 34294787, 2021).
cardiac arrest (1 paper, 2015). Cessation of breathing and/or cardiac function. "The cause of death in patients with PIGA mutations has been mainly due to cardiac arrest, pneumonia and respiratory failure." (PMID 25885527, 2015).
Cerebellar atrophy (1 paper, 2020). Cerebellar atrophy is defined as a cerebellum with initially normal structures, in a posterior fossa with normal size, which displays enlarged fissures (interfolial spaces) in comparison to the foliae secondary to loss of tissue. "Brain MRI showed cerebellar atrophy in 76% of the PIGT-deficient patients (10/14 patients with available data), which also accounted for the majority of patients with PIGA mutations (25%, 4/16 patients with available data)." (PMID 32220244, 2020).
colorectal adenoma (1 paper, 2024). An adenoma that arises from the colon or rectum. "Previous studies on FAP- or MAP-associated colorectal adenomas identified no PIGA variants and a targeted screen of PIGA in colorectal adenomas from FAP and MAP patients in the current study identified only a single PIGA variant that was not likely to cause loss of function." (PMID 38546397, 2024).
colorectal tumour (1 paper, 2017). "Even if no significant uptake was seen in the tumoural caecum with anti-CEA pIgA, this antibody allowed the targeting of lung metastases derived from the initial colorectal tumour." (PMID 29156712, 2017). "The pattern of distribution of 99mTc-anti-CEA pIgA-SH between the different organs in the mouse colorectal tumour model was similar to that observed in healthy mouse." (PMID 29156712, 2017). "Biodistribution of 99mTc-anti-CEA pIgA-SH, 99mTc-irrelevant pIgA-SH and 99mTc-anti-CEA IgG-SH was subsequently evaluated 4 h post-injection by microSPECT/CT in normal SCID mice and in SCID and Tsg SCID-CD89 colorectal tumour model (n=3 for each Ig and mice model)." (PMID 29156712, 2017).
duodenal carcinoma (1 paper, 2024). "The presence of PIGA variants in 7/19 (37%) higher grade lesions (TA with high-grade dysplasia and tubulovillous adenomas) and a duodenal carcinoma from a MAP patient, might also suggest a role for PIGA in tumor progression." (PMID 38546397, 2024).
Duodenal Tumors (1 paper, 2024). "PIGA somatic mutation in duodenal tumors from patients with FAP and MAP and loss of membrane GPI-anchors may present new opportunities for understanding and intervention in duodenal tumorigenesis." (PMID 38546397, 2024).
dyslipidemia (1 paper, 2015). "The additional presence of dysmorphic facial features, CNS abnormalities, hypotonia, heart defects, dyslipidemia/lipoprotein lipase deficiency, or signs of intra-myelin edema on brain MRI, may increase the likelihood of mutations in PIGA specifically, and PIG family members in general." (PMID 25885527, 2015).
eczema (1 paper, 2020). "Among non-PMM2-CDG, skin allergies—particularly eczema—were the most reported, especially in ALG13-, SRD5A3- and PIGA-CDG." (PMID 32635232, 2020).
gastritis (1 paper, 2013). Inflammation of the stomach. "Gastritis can also stimulate immunological activity in the human antrum, where abundant IgA-positive plasma cells were detected and pIgA was secreted by pIgR-expressing epithelium." (PMID 24236214, 2013).
generalized dystonia (1 paper, 2022). "In eight patients with generalized dystonia from infancy, the mutation of PIGA, TCF4, CHRNG, SLC16A2, KCNQ2, NACC1, CTNNB1, or ARSA gene were found to be causative." (PMID 35719373, 2022).
glycosylphosphatidylinositol deficiency (1 paper, 2024). "Patients carrying a mutation of the PIGA gene usually suffer from inherited glycosylphosphatidylinositol deficiency (IGD) with intractable epilepsy and intellectual developmental disorder." (PMID 39850562, 2024).
hyperphosphatasia (1 paper, 2024). "Recently, mutations have been identified in six genes (PIGA, PIGY, PIGO, PGAP2, PIGW and PGAP3) encoding proteins in the Glycosyl phosphatidylinositol(GPI)-anchor-synthesis pathway in individuals with hyperphosphatasia with impaired intellectual development syndrome(HPMRS)." (PMID 39687712, 2024).
IgA nephropathy glomerulonephritis (1 paper, 2018). "Application in other diseases of interest may depend on the route of transmission and the major site(s) of pathogen replication, with limited diagnostic use in patients with IgA nephropathy glomerulonephritis due to increased production of antigen-specific pIgA." (PMID 30285838, 2018).
influenza infection (1 paper, 2020). "Here, we review some potentially valuable bnAbs for influenza; one is a novel passive immunotherapy using a variable domain of heavy chain-only antibody (VHH), and the other is polymeric immunoglobulin A (pIgA) induced by intranasal vaccination." (PMID 32751206, 2020).
leukemia (1 paper, 2021). A malignant (clonal) hematologic disorder, involving hematopoietic stem cells and characterized by the presence of primitive or atypical myeloid or lymphoid cells in the bone marrow and the blood. "used PIGA-mutant and PIGA-corrected leukemia cell lines to test the sensitivity of GPI (-) cells to NK-mediated immune attack." (PMID 35154088, 2021).
Macrocephaly (1 paper, 2024). Occipitofrontal (head) circumference greater than 97th centile compared to appropriate, age matched, sex-matched normal standards. "Interestingly, macrocephaly has been reported in patients with mutations in PIGA, PIGC, and PIGM, which are involved in the initial stages of GPI anchor biosynthesis." (PMID 40225942, 2024).
measles (1 paper, 2018). A highly contagious viral infection caused by the measles virus. "Previous detection of antigen-specific pIgA in serum of individuals infected with rubella, measles and varicella required physical separation of pIgA from IgA, and did not assess diagnostic potential." (PMID 30285838, 2018).
microcephaly (1 paper, 2023). A congenital or acquired developmental disorder in which the circumference of the head is smaller than normal for the person's age and sex. "Some functional studies refuted pathogenicity of apparently good candidate variants, one notable example being a PIGA variant, p.(Lys78Glu) in a patient with microcephaly which did not affect cell-surface expression of GPI-anchored proteins and is classified as likely benign (SCV000891722.1)." (PMID 37946251, 2023).
myelodysplastic syndrome (1 paper, 2024). A clonal hematopoietic disorder characterized by dysplasia and ineffective hematopoiesis in one or more of the hematopoietic cell lines. "The carriers of somatic PIGA and BCOR/BCORL1 mutations show a lower risk of AA transformation to myelodysplastic syndrome (MDS), whereas myeloid driver lesions such as DNMT3A and ASXL1 mutations characterize the group with a higher risk of malignancy." (PMID 38646536, 2024).
myeloid neoplasm (1 paper, 2022). Proliferation of myeloid cells originating from a primitive stem cell. "Carriers of BCORL1 mutation, such as PIGA and BCOR, exhibit a lower risk of progressing to secondary myeloid neoplasms, and thus, this variant could represent a marker of immune selection without being a significant driver of myeloid malignancy." (PMID 36499545, 2022).
myoclonic seizure (1 paper, 2020). "By summarizing the PIGA mutations cases reported, myoclonic seizure was the most common type (10/19 patients with available data)." (PMID 32220244, 2020).
neuroblastoma (1 paper, 2025). Neuroblastoma (NB) is the most common solid, extracranial childhood tumor. "We also observed the deregulation of PIGA and PIGZ in MYCN-A neuroblastoma." (PMID 39860532, 2025).
refractory anemia (1 paper, 2017). "Mutations in genes other than PIGA, EGFR-AS1, AKT2 and CBLC, were largely distributed in subjects with refractory anemia with excess blasts (RAEB) (n = 56) or the AML with multilineage dysplasia following MDS (MDS-AML) (n = 24)." (PMID 29137279, 2017).
cancer (6 papers, 2018 to 2024). A tumor composed of atypical neoplastic, often pleomorphic cells that invade other tissues. "PIGA mutations were also rare among the 10,967 cancers in the TCGA pan cancer dataset (65 variants, 0.6%) and in PCAWG (106 exonic variants/19,729 donors, 0.54%)." (PMID 38546397, 2024). "GPI-anchored proteins and components of the GPI anchor biosynthesis pathway including PIGA are prognostic biomarkers in cancer." (PMID 38546397, 2024). "Although the data presented here indicate that PIGA mutation is sufficient to disrupt GPI surface anchoring, the mechanisms by which this may contribute to duodenal adenoma or carcinoma development remains unclear." (PMID 38546397, 2024). "PIGA has not previously been significantly associated with any cancer." (PMID 38546397, 2024).
infection (6 papers, 2012 to 2025). The state of being infected such as from the introduction of a foreign agent such as serum, vaccine, antigenic substance or organism. "Dysplastic cells are unable to transport pIgA and the pentameric IgM to the surface, compromising mucosal protection against infection." (PMID 39273632, 2024). "Unlike anti-HCV IgM, detectable in 51–82% of patients after 6 months and beyond, data from HCV seroconversion panels suggest that pIgA detected in acute phase is transient, even in an ongoing infection." (PMID 30285838, 2018). "These infections begin and/or persist in mucosal tissues where polymeric immunoglobulin (Ig) A (pIgA) is the predominant antibody produced." (PMID 30285838, 2018). "In contrast, pIgA is known to have a shorter half-life in serum, which may serve as a better marker of recent infection." (PMID 30285838, 2018). "Low correlation between virus-specific IgM and pIgA and varying propensity of antibody-isotype response observed may relate to the duration of infection, and/or to the proportion of antigens circulating systemically or localized to the liver." (PMID 30285838, 2018). "We also examined whether the multiplicity of infection (MOI) of the PIGA targeting vector has an impact on the H/R ratio in our system." (PMID 23056640, 2012). "We detected no increase of FLAER-negative cells by the transfection of PIGA targeting vector; however, the infection of the cells with PIGA targeting vector resulted in an increase of FLAER-negative cell populations to 7.4–8.9% (p <0.0001, versus the plasmid-based targeting vector)." (PMID 23056640, 2012). "Anti-HCV pIgA peaked early in HCV seroconversion panels (n = 14), and was undetectable after 4 weeks post-primary bleed, even in ongoing infections, while serum anti-HCV IgA, IgG and IgM persisted." (PMID 30285838, 2018). "Among the genes with the greatest positive effect on infection efficiency after knockout were multiple GPI biosynthesis genes: GPAA1, PIGA, PIGV, and DPM1 knockouts increased infection over 8-fold compared to control, while PIGO knockout increased infection approximately 4-fold." (PMID 40901862, 2025). "Notably, knockout of PIGA, PIGV, or GPAA1 significantly increased the infection of other coronaviruses relative to controls, with the strongest effects observed for HCoV-229E (7-fold) and PEDV (20-fold)." (PMID 40901862, 2025). "We re-introduced PIGA or GPAA1 cDNA into the respective knockout HeLa cells and found that trans-complementation not only significantly reduced infection with alphacoronaviruses HCoV-229E and PEDV but also with the SARS-CoV-2 original, Delta, Omicron BA.1 and BA.2 variants." (PMID 40901862, 2025). "However, overexpression of PIGA or PIGV in unmodified HeLa cells did not alter infection by multiple coronaviruses relative to controls." (PMID 40901862, 2025). "Anti-HCV pIgA declined over time even in ongoing infections—unlike anti-HCV IgA and ALT, which may persist, as observed in panel 901 and 400062." (PMID 30285838, 2018). "Indeed, we observed substantial efficiency of PIGA gene targeting upon infection of cells with PIGA-targeting vectors carrying no functional promoters (hACTB-R and N.P.)." (PMID 25170953, 2014).
blood disorder (5 papers, 2020 to 2025). "Previous research has shown that ITP patients harboring mutations in genes such as DNMT3A, TET2, ASXL1, BCOR, PIGA, and U2AF1 tend to progress into other clonal hematologic disorders, leading to treatment ineffectiveness." (PMID 40574285, 2025).
tumor (4 papers, 2017 to 2025). "However, under pathological conditions, environmental enrichment can induce pIgA-dependent wound repair in a colon-tumor-bearing mice model." (PMID 34638806, 2021). "The in vivo imaging by microSPECT/CT confirm that the anti-CEA pIgA is a suitable tool for the detection of mucosal tumours, particularly in lungs, but in vivo imaging is less sensitive (1 mm resolution) and uptake was detectable only for a intermediate tissue colonisation (0.08% ± 0.01%)." (PMID 29156712, 2017). "Anti-CEA pIgA tumour uptake was studied in mice bearing the WiDr caecal orthotopic graft." (PMID 29156712, 2017). "The dysregulation of PIGA and PIGZ may alter the function and expression of GPI-anchored proteins, potentially contributing to tumor progression and immune evasion mechanisms." (PMID 39860532, 2025).
neurodevelopmental disorder (2 papers, 2017 to 2023). A behavioral and cognitive disorder with onset during the developmental period that involves impaired or aberrant development of intellectual, motor, or social functions. "Multiple congenital anomalies–hypotonia–seizures syndrome-2 (MCAHS2) [OMIM: 300868], caused by mutations on the phosphatidylinositol-glycan-anchor biosynthesis class A (PIGA) gene, is an idiopathic X-linked recessive (XL) neurodevelopmental disorder." (PMID 37239976, 2023).
PIGA also shares sentences with these, for which no sentence is quoted: developmental delay (3 papers); hemolysis (3); anemia (2); epileptic encephalopathies (2); genetic diseases (2); oesophageal adenocarcinoma (2); pancreatic cancer (2); absence seizures (1); acute hepatitis A (1); atypical hemolytic-uremic syndrome (1); Autoimmunity (1); Barrett’s metaplasia (1); bone marrow failure (1); cerebellar ataxia (1); cleft palate (1); COVID-19 (1); dermatosis (1); diabetes (1); duodenal adenocarcinoma (1); Dystonia (1); epileptic syndrome (1); ferro-cerebro-cutaneous syndrome (1); gastro-oesophageal reflux disease (1); Gaucher disease (1); head and neck cancer (1); hepatoma (1); hyperphosphatasia mental retardation syndrome (1); Hypotonia (1); ichthyosis (1); inflammatory bowel disease (1).
A further 27 diseases each share a sentence with PIGA in 1 paper.